LARP1 (La ribonucleoprotein 1, translational regulator)
Description:
RNA-binding protein that regulates the translation of specific target mRNA species downstream of the mTORC1 complex, in function of growth signals and nutrient availability. Interacts on the one hand with the 3' poly-A tails that are present in all mRNA molecules, and on the other hand with the 7-methylguanosine cap structure of mRNAs containing a 5' terminal oligopyrimidine (5'TOP) motif, which is present in mRNAs encoding ribosomal proteins and several components of the translation machinery. The interaction with the 5' end of mRNAs containing a 5'TOP motif leads to translational repression by preventing the binding of EIF4G1. When mTORC1 is activated, LARP1 is phosphorylated and dissociates from the 5' untranslated region (UTR) of mRNA. Does not prevent binding of EIF4G1 to mRNAs that lack a 5'TOP motif. Interacts with the free 40S ribosome subunit and with ribosomes, both monosomes and polysomes. Under normal nutrient availability, interacts primarily with the 3' untranslated region (UTR) of mRNAs encoding ribosomal proteins and increases protein synthesis. Associates with actively translating ribosomes and stimulates translation of mRNAs containing a 5'TOP motif, thereby regulating protein synthesis, and as a consequence, cell growth and proliferation. Stabilizes mRNAs species with a 5'TOP motif, which is required to prevent apoptosis. (Microbial infection) Positively regulates the replication of dengue virus (DENV).
Synonyms: KIAA0731; LARP; MGC19556; Lar1; Lhp1
Tractability: Small molecule: a structure with a bound ligand is known. PROTAC: UniProt records ubiquitination sites on it; ubiquitination databases record sites on it; its protein half-life has been measured.
Gene: Protein-coding gene on chromosome 5 (154,682,986 to 154,817,605, forward strand). Ensembl gene ENSG00000155506.
Subcellular location: Cytoplasm; Cytoplasmic granule
Subcellular location (Human Protein Atlas): Cytosol; Endoplasmic reticulum; Nucleoplasm
Pathways (Reactome):
Disease: SARS-CoV-2 activates/modulates innate and adaptive immune responses
Gene Ontology:
Molecular function: cadherin binding; eukaryotic initiation factor 4E binding; mRNA 3'-UTR binding; mRNA 5'-UTR binding; protein binding; ribosomal small subunit binding; RNA 7-methylguanosine cap binding; RNA binding; RNA cap binding; translation activator activity; translation initiation factor binding
Biological process: cell population proliferation; cellular response to rapamycin; mRNA stabilization; negative regulation of translation; negative regulation of translational initiation; positive regulation of macroautophagy; positive regulation of translational initiation; positive regulation of viral genome replication; post-transcriptional regulation of gene expression; response to amino acid starvation; TOR signaling; TORC1 signaling; translational initiation; positive regulation of translation
Cellular component: cytoplasm; cytoplasmic stress granule; cytosol; membrane; TORC1 complex
Genetic constraint (gnomAD): Loss-of-function variants: 36 observed, 117.25 expected, observed/expected ratio (o/e) 0.31, 90% interval 0.23 to 0.41. The upper end of that interval is the gene's LOEUF score, 0.41, which puts it in group 1 of 6, group 1 being the genes least tolerant of losing a copy. Missense variants: 1,021 observed, 1,396.5 expected, observed/expected ratio (o/e) 0.73, 90% interval 0.69 to 0.77. Synonymous variants: 529 observed, 518.73 expected, observed/expected ratio (o/e) 1.02, 90% interval 0.95 to 1.1.
Homologues: Orthologues: dog LARP1 (96% identical), pig LARP1 (95% identical), rabbit LARP1 (95% identical), chimpanzee LARP1 (94% identical), macaque LARP1 (93% identical), rat Larp1 (90% identical), mouse Larp1 (89% identical), guinea pig LARP1 (84% identical), tropical clawed frog larp1 (68% identical), zebrafish larp1 (59% identical), Drosophila melanogaster Larp4B (10% identical), Caenorhabditis elegans larp-5 (8% identical). Paralogues in human: LARP1B (49% identical), LARP4B (12% identical), LARP4 (11% identical), LARP6 (8% identical), LARP7 (6% identical), SSB (5% identical).
Diseases named in the same sentence as LARP1 in open-access papers:
LARP1 is named in the same sentence as 54 diseases in open-access papers, as found by Europe PMC text mining. Sharing a sentence is not in itself a finding about the gene and the disease. The quoted sentences say what the papers report.
ovarian carcinoma (20 papers, 2016 to 2025). A malignant neoplasm originating from the surface ovarian epithelium. "LARP1 is essential for the survival of epithelial ovarian cancer cells and promotes ovarian cancer tension and chemotherapy resistance." (PMID 38283117, 2024). "LARP1 had also been reported to have significant correlation with some tumor, such as colorectal cancer and ovarian cancer." (PMID 35602299, 2022). "LARP1 silencing inhibited cell migration in prostate cancer and cell proliferation in colorectal cancer, and sensitized ovarian cancer cells to cisplatin, paclitaxel and gemcitabine." (PMID 33499187, 2021). "For example, LARP1, an RNA binding protein in ovarian cancer, is a post-transcriptional regulator of survival and tumorigenesis; RNA binding proteins SRSF1 and SRSF9 can promote Wnt signaling-mediated tumorigenesis by enhancing β-catenin biosynthesis." (PMID 32219019, 2020). "The RBP ribonucleoprotein 1, translational regulator 1 (LARP1) promotes ovarian cancer progression and by altering the stability of its target mRNAs B cell lymphoma 2 (BCL2) and BCL-2–interacting killer (BIK)." (PMID 33193718, 2020). "Studies have reported that the expression of LARP1 in ovarian cancer cells is significantly upregulated, which is necessary for cancer cell survival and chemotherapy resistance." (PMID 32953888, 2020). "The biological role of LARP1 was investigated in non-small cell lung cancer, ovarian cancer, and hepatocellular carcinoma." (PMID 33680937, 2020). "To explore the role of LARP1 in the ovarian cancer cell, we performed mRNA-sequencing following LARP1 knockdown in the malignant ovarian OVCAR8 cell line." (PMID 26717985, 2016). "Having demonstrated LARP1 promotes ovarian cancer cell survival, we investigated LARP1 expression in ovarian malignancies." (PMID 26717985, 2016). "Using IHC analysis of ovarian TMAs, we found significantly higher expression of LARP1 protein in ovarian cancer samples compared to normal ovarian tissue (P < 0.001)." (PMID 26717985, 2016). "Here we explore the role of LARP1 in epithelial ovarian cancer (EOC), a disease responsible for over 140 000 deaths worldwide every year." (PMID 26717985, 2016). "Together, our data indicate that by differentially regulating the stability of a selection of mRNAs, LARP1 promotes ovarian cancer progression and chemotherapy resistance." (PMID 26717985, 2016). "By differentially regulating the stability of pro- and anti-apoptotic mRNA transcripts, LARP1 acts as a post-transcriptional promoter of apoptosis evasion in ovarian cancer cells." (PMID 26717985, 2016). "Here we explore the role of LARP1 in epithelial ovarian cancer, a disease characterized by the rapid acquisition of resistance to chemotherapy through the induction of pro-survival signalling." (PMID 26717985, 2016). "Together with our in vitro and in vivo data, this suggests a model whereby LARP1 differentially regulates the mRNA stability of pro- and anti-apoptotic transcripts in malignant ovarian tumours to promote cell survival." (PMID 26717985, 2016). "Moreover, LARP1 expression levels were considerably elevated in ovarian cancer and were correlated with poor clinicopathological characteristics in patients with ovarian cancer." (PMID 36473947, 2022). "LARP1 knockdown in ovarian cancer derived cell lines (SKOV3 and OVCAR8, both highly resistant to platinum-based therapies), decreased cell viability while increasing apoptosis, and enhanced the sensitivity of cells to commonly used drugs for EOC treatment (CP, Paclitaxel and Gemcitabine)." (PMID 34328175, 2021). "Indeed, our interest in LARP1 was stimulated by Sarah Blagden’s observation that LARP1 protein levels are correlated with ovarian cancer progression." (PMID 32233986, 2021).
ovarian carcinoma (continued). "More recently, our findings have been substantiated using pulsed Stable Isotope Labelling with Amino acids in Cell culture (SILAC) in ovarian cancer (OVCAR8) cell lines where we observed that LARP1 regulates the de novo synthesis of a number of proto-oncogenic and cell survival proteins." (PMID 32233986, 2021). "Here we interrogate the LARP1 interactome in the context of ovarian cancer to characterize the interactions between LARP1 and its target genes and observe the impact of these interactions on stem cell marker expression, chemotherapy resistance and patient survival outcome." (PMID 26717985, 2016). "Indeed, we found that LARP1 is required for apoptosis evasion and to ensure cell survival following exposure to chemotherapy in platinum-resistant ovarian cancer cells." (PMID 26717985, 2016). "As LARP1 appeared to be capable of both positively and negatively regulating transcript stability, we were interested to see if LARP1 was localized to these sites of RNA fate determination in ovarian cancer cells." (PMID 26717985, 2016). "We then assessed the effect of LARP1 expression on PFS in ovarian cancer." (PMID 26717985, 2016). "In ovarian cancer cells, we showed that knockdown of BCL2 causes apoptosis and enhanced chemosensitivity, while overexpression of BCL2 partially rescues the effects of LARP1 depletion." (PMID 26717985, 2016). "Our findings identify LARP1 as a key post-transcriptional regulator of ovarian cancer behaviour." (PMID 26717985, 2016). "High expression of RBP LARP1 co-associates with BCL2 and BIK in BCL2 messenger ribonucleoprotein (mRNP) complexes in epithelial ovarian cancer and stabilizes BCL2 while destabilizing BIK, which promotes ovarian cancer cell survival and leads to adverse prognosis." (PMID 33643390, 2021). "In an analysis of a TMA of 67 ovarian cancer cases collected at initial debulking surgery, we showed that only LARP1 expression and cancer stage were significant independent predictors of poor overall survival in patients with ovarian malignancy (LARP1 HR = 1.13, 95% CI 1.01–1.27, P = 0.036)." (PMID 26717985, 2016). "Our discovery of a correlation between circulating levels of LARP1 and tumour burden in ovarian cancer patients suggests that plasma LARP1 levels could prove a useful non-invasive means of measuring tumour LARP1 expression, which we intend to prospectively validate." (PMID 26717985, 2016). "LARP1 also regulates mitochondrial oxidative phosphorylation in response to the PI3K/mTOR pathway, contributing to ovarian cancer cell survival." (PMID 40018039, 2025). "For example, LARP1 enhances the stability of BCL2 but attenuates the stability of BIK, leading to the malignant progression of ovarian cancer." (PMID 34890108, 2022). "Recent studies have revealed that LARP1 drives oncogenesis, and higher levels of LARP1 protein correspond with a poor prognosis in NSCLC, colorectal cancer, prostate cancer, ovarian cancer, HCC, and ICC." (PMID 35785179, 2022). "LARP1 is of significance in osteosarcoma, prostate cancer, non-small cell lung cancer, CRC and ovarian cancer." (PMID 35264065, 2022). "To gain further insights into the expression of LARP1 isoforms we conducted Oxford Nanopore sequencing technology (ONT) in HEK-293 T and OVCAR-8 cells, immortalized human embryonic kidney and ovarian cancer cell lines, respectively." (PMID 32286153, 2021). "Interestingly, this finding was not limited to ovarian cancer; by analysing overall survival in 1115 breast cancer patients, we found that high LARP1 expression was also predictive of poor outcome (HR = 1.53, P < 0.001, 95% CI 1.2–1.96), suggesting an oncogenic role for LARP1 in other tumour types." (PMID 26717985, 2016). "We hypothesized that, as LARP1 acted as a post-transcriptional regulator of the apoptosis players BCL2 and BIK, modulation of LARP1 expression in ovarian cancer cells would affect their survival." (PMID 26717985, 2016).
ovarian carcinoma (continued). "To confirm LARP1 protein interacts with BCL2 and BIK mRNAs, as suggested by the published LARP1 interactome, we performed RNA-immunoprecipitation in OVCAR8 and SKOV3 ovarian cancer cell lines." (PMID 26717985, 2016). "To determine whether LARP1 could be regulating the stability of BCL2 and BIK transcripts in patient tumours, we evaluated trends in LARP1, BCL2 and BIK transcript abundance in the TCGA ovarian cancer dataset." (PMID 26717985, 2016). "In ovarian cancer cells, we showed that knockdown of BCL2 also reduces CSC-like populations, suggesting that the LARP1-mediated anti-CSC phenotype may also be mediated via BCL2 expression." (PMID 26717985, 2016). "Interestingly, also the La-related protein 1 (LARP1) has recently been found to promote survival and cisplatin resistance by stabilizing Bcl2 mRNA in in ovarian cancer cells." (PMID 27105491, 2016).
lung carcinoma (12 papers, 2016 to 2025). "Recently, it has been found that downregulation of LARP1 expression in endometrial cancer and lung cancer cell lines was associated with decreased cell proliferation." (PMID 27614686, 2016). "A previous study demonstrated that LARP1 is associated with the proliferation of endometrial cancer and lung cancer lines." (PMID 27614686, 2016). "Meanwhile, according to the study, the XIST/miR-374A/LARP1 axis is associated with lung cancer." (PMID 36353111, 2022). "On the whole, these data implicated that LARP1 was a target of miR-1287-5p in lung cancer." (PMID 35365169, 2022). "LARP1 has been recognized as a driver of cancer progression, exhibiting increased expression in hepatoblastoma, lung cancer, and multiple myeloma, among other cancers." (PMID 39786317, 2025). "Meanwhile, LARP1 is recognized for its role in facilitating the metastasis of non‐small cell lung cancer via the activation of the mTOR pathway." (PMID 39786317, 2025). "In lung cancer, silencing of LARP1 constrained growth and mobility of cancer cells, indicating LARP1 was an oncogene." (PMID 35365169, 2022). "Conclusively, circ_0047921 regulated the development of lung cancer through regulating miR-1287-5p/LARP1 axis." (PMID 35365169, 2022). "Collectively, in this study we firstly confirmed that circ_0047921/miR-1287-5p/LARP1 axis facilitated the development of lung cancer by regulating growth, migration, invasion, EMT and glycolysis of lung cancer cells." (PMID 35365169, 2022). "Circ_0047921 was overexpressed in lung cancer, and circ_0047921 targeted miR-1287-5p to modulate LARP1 expression, thereby facilitating the development of lung cancer." (PMID 35365169, 2022). "The circ-BANP-mediated miR-503/LARP1 signaling pathway promotes the proliferation and metastasis of lung cancer." (PMID 35342419, 2022). "LARP1 is an RNA-binding protein that interacts with poly-A-binding protein and was reported to function as an oncogene to promote lung cancer cell growth, migration, and invasion." (PMID 36761423, 2022). "Mechanically, circ_0047921 sponged miR-1287-5p to increase LARP1 expression, thereby aggravating the development of lung cancer." (PMID 35365169, 2022). "For instance, circ-BANP accelerated the development of lung cancer through targeting miR-503/LARP1 axis." (PMID 33393621, 2021). "What is more, remarkably unregulated circBANP promoted lung cancer cells proliferation and invasion by abrogating the antitumor effects of miR-503/LARP1." (PMID 31534962, 2019). "LARP1 protein is highly expressed in hepatocellular and lung cancers, where it is an independent predictor of adverse prognosis." (PMID 26717985, 2016). "The RBP LARP1 is an mRNA stability regulator, and elevated expression of the protein in hepatocellular and lung cancers is correlated with adverse prognosis." (PMID 26717985, 2016). "The upregulation of LARP1 could abolish inhibitory effects of circ_0047921 silencing on lung cancer progression." (PMID 35365169, 2022). "Circ_0047921 regulated LARP1 by sponging miR-1287-5p in lung cancer." (PMID 35365169, 2022). "Additionally, LARP1 was a functional target of miR-1287-5p and was inversely related to miR-1287-5p expression in lung cancer tissues." (PMID 35365169, 2022). "Furthermore, LARP1 was negatively correlated with miR-1287-5p while positively correlated circ_0047921 expression in lung cancer tissues." (PMID 35365169, 2022). "The data showed that LARP1 level was significantly increased in lung cancer tissues." (PMID 35365169, 2022). "Moreover, we explored the interplays among circ_0047921, miR-1287-5p, and LARP1, so as to provide new biomarkers for lung cancer diagnosis or treatment." (PMID 35365169, 2022). "Therefore, circ_0047921 mediated LARP1 expression to promote lung cancer progression." (PMID 35365169, 2022).
lung carcinoma (continued). "In summary, our current work implied that the carcinogenic role of circ_0047921 was partly attributed to its regulatory effects on miR-1287-5p/LARP1 axis, and circ_0047921 might serve as a novel biomarker and a promising therapeutic target for lung cancer patients." (PMID 35365169, 2022). "Other studies have shown that miR‐503 inversely regulates lung cancer progression by inhibiting different targets including PDK1 (pyruvate dehydrogenase kinase 1) and LARP1 (La‐related protein 1) respectively." (PMID 37212485, 2023). "Circ_0047921/miR-1287-5p/LARP1 axis played a key role in proliferation, migration, invasion, EMT and glycolysis of lung cancer cells." (PMID 35365169, 2022). "In another study, LARP1 was established as a target of miR-503 and further regulated by circ-BANP to promote lung cancer progression." (PMID 35785179, 2022). "Conversely, LINC01270 exhibits competitive endogenous (ce)RNA functions, as seen in its ability to sponge miRNA (miR)-326 to modulate the mRNA levels of LA-related protein 1 (LARP1) and Ephrin A3 (EFNA3), thus exacerbating lung cancer and gastric cancer progression, respectively." (PMID 39682774, 2024). "In addition, the results of RT-qPCR and western blot assay also suggested that LARP1 levels were upregulated in lung cancer tissues and cells than that in adjacent non-tumorous tissues and BEAS-2B cells, respectively." (PMID 35365169, 2022).